PAK2 (p21 (RAC1) activated kinase 2)
Diseases named in the same sentence as PAK2 in open-access papers (continued):
Sharing a sentence is not in itself a finding about the gene and the disease.
tumor (continued). "In this study, we identified miR-4779 as a novel tumor suppressor miRNA and demonstrated that miR-4779 induces cancer cell apoptosis and cell cycle arrest by targeting PAK2 and CCND3 in vitro and in vivo." (PMID 29362401, 2018). "The novel tumor suppressor miR-4779 inhibits cancer cell growth via cell cycle arrest and apoptosis by directly targeting PAK2 and CCND3." (PMID 29362401, 2018). "The presence of PAK2 regulates haematopoietic tumour growth in vivo and cannot be compensated for by PAK1." (PMID 28707321, 2017). "The unique role of PAK2 in haematopoietic tumour development only becomes apparent upon growing towards the resistance of a surrounding tissue." (PMID 28707321, 2017). "Our observation regarding the pivotal role of PAK2 in colony formation is shared by other groups studying different tumour types." (PMID 28707321, 2017). "Our study identifies PAK2 as key molecule for tumour cell growth and proliferation of endothelial tissue." (PMID 28707321, 2017). "Expression of PAK2 in leukaemic cells facilitates tumour development in vivo, formation of colonies in vitro, and endothelial cell proliferation." (PMID 28707321, 2017). "It is noteworthy that the SH3 domain of NESH interacts with PAKs and that NESH affects cell motility and tumor metastasis by regulating PAK2 activity." (PMID 22485184, 2012). "Additionally, analyses of three independent datasets corroborated that the expression levels of PAK2 were markedly increased in tumor samples." (PMID 41311809, 2025). "Moreover, the calibration curves along with the goodness-of-fit assessments for the predicted outcomes in both tumor and normal cohorts indicated that PAK2 serves as a reliable biomarker for the diagnosis of HNSC." (PMID 41311809, 2025). "In order to investigate possible therapeutic strategies that might mitigate PAK2-driven tumor promotion, we conducted a cMAP analysis." (PMID 41311809, 2025). "This correlation suggests that PAK2 may play a pivotal role in promoting tumor progression by effectively modulating these critical pathways." (PMID 41311809, 2025). "Notably, FRAX597 treatment further decreased the proportion of CTC clusters, suggesting that PAK2 inhibition can suppress tumor cell aggregation." (PMID 41423632, 2025). "Furthermore, PAK2 facilitated communication between cancer cells and cells in the tumor microenvironment, augments cancer cell chemoresistance, and induced alterations in pathways associated with energy metabolism." (PMID 38343537, 2024). "Moreover, they reported that PAK2 improved tumor cell growth, invasion, and migration via regulating actin dynamics through the LIMK1/cofilin signaling pathway." (PMID 39769207, 2024). "Rac1 and Cdc42 activate PAK2, facilitating cytoskeletal dynamics and tumor progression." (PMID 39769207, 2024). "Additionally, PAK2 fostered communication between cancer cells and the tumor microenvironment, augments cancer cell chemoresistance, and modulates energy metabolism pathways." (PMID 38343537, 2024). "In addition, hsa_circ_0013401 enhanced tumour formation and progression through the regulatory axis of miR-195/PAK2; however, evidence supporting the role of this circRNA in other cancers is lacking." (PMID 36983973, 2023). "Furthermore, The Cancer Genome Atlas analysis between normal gastric and GC tissues showed that PAK2 was highly expressed in GC, which was further confirmed in clinical samples of normal gastric mucosa tissues and GC tumor samples by RT-qPCR." (PMID 36740679, 2023). "This “active” tumor suppressing complex is then dismantled upon phosphorylation at S518 by PAK2." (PMID 36809290, 2023). "Additionally, knockdown of SOX2 notably counteracted PAK2 upregulation-induced tumor-promoting effects on cell proliferation, migration, and expression of EMT-related factors." (PMID 34621737, 2021). "Besides, PAK2 upregulation partially reversed RP11-499E18.1 overexpression-triggered tumor-suppressing effects on OC cells." (PMID 34621737, 2021).
tumor (continued). "Finally, the effects of RP11-499E18.1 and PAK2 expression on the tumor growth in nude mice were determined." (PMID 34621737, 2021). "These outcomes manifested that RP11-499E18.1 overexpression might carry out its tumor-suppressing efficacy through decreasing the interaction between PAK2 and SOX2, and thereby lessen the nuclear translocation of SOX2." (PMID 34621737, 2021). "Based on this result, we speculated that RP11-49E18.1 might perform its tumor-suppressive roles through interacting with PAK2." (PMID 34621737, 2021). "These outcomes indicated that PAK2 might perform a tumor-promoting efficacy in OC, which is consistent with the prognosis analysis results." (PMID 34621737, 2021). "Based on these evidences, we speculated that PAK2 upregulation might perform its tumor-promoting efficacy through increasing the phosphorylation and nuclear distribution of SOX2 in OC cells." (PMID 34621737, 2021). "Combination of these results indicated that PAK2 overexpression might perform its tumor-promoting efficacy through increasing the phosphorylation of SOX2." (PMID 34621737, 2021). "Next, we tested if CDK12 induces tumor growth by activating PAK2-induced MAPK signaling pathway." (PMID 32483448, 2020). "Tumor size and tumor weight were significantly lower in PAK2 knock-down tumors." (PMID 32483448, 2020). "For example, DLG1 is a tumor suppressor gene whose knockdown in Drosophila leads to neoplasms in the developing brain and eye disc, while PAK2 is a key downstream mediator of the ERK signaling pathway for neuronal extension and is activated by caspases during apoptosis." (PMID 32053595, 2020). "PAK2 expression was significantly higher in tumor tissues compared with adjacent tissues." (PMID 32483448, 2020). "PAK2 might therefore be the critical isoform in leukaemic cells by controlling tumour growth in a dual manner: vascularization via exosome‐mediated transfer to endothelial cells and remodelling of the extracellular matrix." (PMID 28707321, 2017). "Tumour‐derived PAK2 may act in a dual manner: it provides angiogenic factors by intracellular signalling, and it is shipped from the tumour to the endothelium via exosomes." (PMID 28707321, 2017). "Since knock down of either Pak1 or Pak2 slowed cell growth and tumor growth, we asked whether such inhibitory effects would be observed using Pak small-molecule inhibitors." (PMID 25596744, 2015). "These intriguing findings strongly suggest that PAK2 may play a pivotal role in modulating the tumor immune microenvironment, potentially facilitating immune evasion and contributing to the progression of the tumor." (PMID 41311809, 2025). "DMG single-cell RNAseq data showed PRKACA, and AKT1 were expressed preferentially in malignant cells while PAK2 was also present in the immune and oligodendrocytic populations suggesting targeting PAK2 can lead to off-tumor toxicity but PRKACA and AKT1 may be more selective targets." (PMID 39954016, 2025). "Besides TGF-β, tumoural PDGF-C could promote LX-2 activation as well, partly via PAK-2 signalling, which initiated a pro-tumour effect from the HSCs on the tumour cells." (PMID 34885024, 2021). "However, miR-4779 may have potential as a tumor suppressor in cancer patients with low miR-4779 and high PAK2/CCND3 expressions." (PMID 29362401, 2018). "Pharmacologic inhibition of PAK2 with FRAX597 impaired CTC cluster formation, suppressed tumor growth, reduced metastasis and decreased CTC cluster numbers in vivo." (PMID 41423632, 2025). "Our data provides a comprehensive comparison of DepMap dependency scores for PAK1, PAK2, PAK3, PAK4, PAK5, and PAK6, based on CRISPR analysis of 1100 tumor cell lines and RNAi analysis of 711 cell lines." (PMID 39756822, 2025). "In summary, our study delineates a previously unrecognized tumor-suppressive pathway in HCC proliferation, linking PPP1R12B to cell cycle control via PAK2/β-catenin/Cyclin D1 axis." (PMID 40612101, 2025).
tumor (continued). "A large number of literature references have shown that PAK2 and PAK4 are directly involved in the regulation of tumor invasiveness and metastasis by influencing their client protein behaviors." (PMID 34437425, 2021). "Taken together, CDK12 phosphorylates PAK2 at T134/T169 and activates MAPK signaling pathway speeding up cancer cell proliferation and tumor growth." (PMID 32483448, 2020). "CDK12 directly binds with and phosphorylates PAK2 at T134/T169, and thus activates MAPK signaling pathway that facilitates cell proliferation and tumor growth." (PMID 32483448, 2020). "Accordingly, PAK2 and CCND3 expression levels were markedly higher in tumor tissues than in normal tissues." (PMID 29362401, 2018). "Nonetheless the role of PAK1/PAK2 as potential target for KRAS MT NSCLC, especially for tumor showing dependency from KRAS, merits further evaluation as potential therapeutic target." (PMID 26468985, 2015). "To assess the role of Pak1 and Pak2 in vivo, we stereotactically injected shRNA-transduced KT21 cells to the skull base of SCID mice and monitored tumor growth by bioluminescence imaging (BLI)." (PMID 25596744, 2015). "PAK1 and PAK2 have been shown to differentially modulate adhesion, RhoA activity and MLC phosphorylation during mast cell degranulation and tumor cell migration." (PMID 24019894, 2013). "The absence of PAK2 amplifies the immunosuppressive capability of these myeloid suppressor cells by enhancing their proliferation, thereby fostering tumor progression and immune evasion." (PMID 40332759, 2025). "In summary, through multi-omics integration analysis, this study first reveals that PAK2 plays a central role in the pathogenesis of HNSC by regulating PCD, tumor stem cell properties, and the immune microenvironment, and provides a candidate drug for its targeted therapy." (PMID 41311809, 2025). "This suggests that PAK2 may be a key molecule driving the acquisition and maintenance of CSC properties in HNSC cells, thereby contributing to tumor invasion, metastasis, and recurrence." (PMID 41311809, 2025). "CDK12 phosphorylates PAK2, activating MAPK signaling and promoting tumor growth and cell division." (PMID 39769207, 2024). "Ras/PI3K/Akt signaling can increase FYN overexpression in cancer, thereby promoting tumor cell migration and invasion.FYN forms a molecular complex with Nck and PAK-2 and p-Tyr molecular complexes with Nck and PAK-2 and assembles in a p-Tyr1214-dependent manner." (PMID 36740671, 2023). "In contrast, the epithelial CMS2 line HT55 was not dependent on PAK2 for subcutaneous tumor growth, emphasizing the relevance of our findings for tumor growth in vivo." (PMID 36869386, 2023). "In addition, due to the lack of PAK7 data in the GSVA database, we grouped 28 tumor patients according to the methylation status of PAK1, PAK2, PAK3, PAK4, and PAK6, respectively, and then analyzed the survival difference of tumor patients." (PMID 36064705, 2022). "Tumor volume measurement results demonstrated that RP11-499E18.1 overexpression distinctly inhibited tumor development of CaOV3 cells as time prolongs, while PAK2 upregulation notably reversed this effect (both p < 0.001)." (PMID 34621737, 2021). "To further investigate the relationship between CDK12 and PAK2 in tumor growth, we utilized GPS, a kinase-specific phosphorylation prediction tool, to find that CDK12 may phosphorylate PAK2." (PMID 32483448, 2020). "MiR-4779 by targeting PAK2 and CCND3 could suppress tumor growth by inducing apoptosis and G1/S arrest." (PMID 33330110, 2020). "Finally, we showed that miR-4779 negatively regulates the expression of the oncogenes PAK2 and CCND3, further suggesting that miR-4779 acts as a tumor suppressor." (PMID 29362401, 2018). "From these data, we conclude that PAK2 and, to a lesser extent, PAK1 expression in leukaemic cells controls/delays the proliferation of surrounding endothelial cells, suggesting an in vivo role in tumour angiogenesis." (PMID 28707321, 2017).
tumor (continued). "Furthermore PAK1 and PAK2 appear to have opposing effects on modulating the phosphorylation of MLC and focal adhesions in tumor cells." (PMID 25379771, 2014). "We did not identify a reciprocal event in the tumour with the PAK2::LRIG1 fusion, which might suggest it is expressed below the level of detection or it is not generated." (PMID 41419736, 2025). "Specifically, PAK2 expression exhibited negative correlations across multiple critical steps of the cancer immune cycle, including the release of cancer antigens, antigen presentation, and the infiltration of immune cells into the tumor microenvironment." (PMID 41311809, 2025).
cancer (59 papers, 2011 to 2025). A tumor composed of atypical neoplastic, often pleomorphic cells that invade other tissues. "In contrast, ‘microRNAs in cancer’ and ‘Mapk signaling pathway’ were promoted in the signaling pathways associated with PAK2." (PMID 40514455, 2025). "To pursue additional predictors of inhibitor responses for PAK2 and other targets, we evaluated the 143 prioritized dependencies for association with the common cancer‐related gene mutations present in HPV(−) HNSCC." (PMID 37997254, 2024). "In various types of cancers, PAK2 has been implicated in the regulation of cancer cell proliferation, cell cycle, and apoptosis." (PMID 39769207, 2024). "Collectively, these results suggest that PAK2 is a critical oncogene which brings about global changes in expression of cancer-associated genes." (PMID 30068946, 2018). "Recent studies have established the function of PAK2 in cancer and identified it as an invasiveness-associated gene which is implicated with cancer proliferation and survival." (PMID 24621074, 2014). "Thereis limited evidence for the involvement of MAPK1 in cancer beyond invitro studies while PAK2 has been shown to be expressed in ovariancancer in one report and interacts with known cancer-associated genes." (PMID 21423607, 2011). "Whereas PAK2 is rarely mutated in cancer, it is frequently amplified and/or overexpressed." (PMID 37997254, 2024). "However, the amplification of PAK2 (as well as PAK2-related genes) is considerably more common in cancer than is inactivation and missense mutations of Pak2 phosphorylation sites in Myc are virtually non-existent." (PMID 35203395, 2022). "Additionally, PAK2 modulated endothelial cell migration, proliferation, and angiogenesis, played a role in pancreatic exocrine secretion, and was implicated in multiple cancer-related signaling pathways." (PMID 40612101, 2025). "Our objective was to scrutinize the interplay between PAK2 expression and the anticancer immune landscape throughout the seven phases of the cancer immune cycle." (PMID 41311809, 2025). "Although the precise mechanisms require elucidation, PAK2 has been well-documented to be overexpressed or hyperactivated in various cancer types." (PMID 40612101, 2025). "CRISPR knockout also identified PAK1 and PAK2 as strongly selective genes, underscoring their potential as cancer‐specific vulnerabilities." (PMID 39756822, 2025). "Among PAK isoforms, group I PAKs (especially PAK1 and PAK2) are the best characterized and most deregulated in cancers." (PMID 40864802, 2025). "Complementary pharmacological inhibition experiments demonstrated that targeted suppression of PAK2 activity abolished Cd‐driven malignant progression in BC models, confirming the essential role of PAK2 in the cancer‐promoting effects of Cd." (PMID 40919610, 2025). "Consistent with previous studies, we identified PAK1 and PAK2 as selective and cancer‐specific vulnerabilities, underscoring their potential as key drivers of tumorigenesis and cancer progression." (PMID 39756822, 2025). "PAK1 and PAK2 emerge as critical regulators of cancer progression and survival, making them compelling targets for therapeutic development." (PMID 39756822, 2025). "A better understanding of the functions of PAK2 in cancer progression will facilitate the development of PAK2-targeted therapeutics." (PMID 39769207, 2024). "A better understanding of the mechanisms of function of PAK2 will facilitate future development of cancer therapies." (PMID 39769207, 2024). "PAK2 played a pivotal role in promoting the angiogenic capability and epithelial-mesenchymal transition processes of cancer cells by activating the TGF-beta signaling pathway." (PMID 38343537, 2024). "In our investigation, grouping analysis of cancer cells revealed that elevated PAK2 expression enhances the angiogenesis capability and epithelial-mesenchymal transition of cancer cells, aligning with findings from previous studies." (PMID 38343537, 2024).